RRM2B (ribonucleotide reductase regulatory TP53 inducible subunit M2B)
Diseases named in the same sentence as RRM2B in open-access papers (continued):
Sharing a sentence is not in itself a finding about the gene and the disease.
Alzheimer disease (2 papers, 2024 to 2025). A progressive, neurodegenerative disease characterized by loss of function and death of nerve cells in several areas of the brain leading to loss of cognitive function such as memory and language. "With this approach, ribonucleoside-diphosphate reductase gene (RRM2B) emerged as a candidate target and its inhibitor, 2′, 2′-difluoro 2′deoxycytidine (gemcitabine), as a potential pharmaceutical drug against Alzheimer's disease." (PMID 38412549, 2024). "RRM2B could also be involved in the disease progression of other neurodegenerative disorders, such as Alzheimer’s disease, indicating potential cross-disorder relevance." (PMID 39801710, 2025). "Thus, the inhibitory drug of the RRM2B activity could be of potential use to treat Alzheimer's disease and particularly gemcitabine might be considered as a promising candidate to be repurposed for its treatment." (PMID 38412549, 2024).
deafness (2 papers, 2013 to 2023). An inherited or acquired condition characterized by the complete loss of the ability to hear from one or both ears. "We identified five predicted highly suspected deafness-associated genes, namely, COL1A1, GJC3, RRM2B, SALL4 and SALL1, in the available databases, including Ensemble and OMIM, indicating that they were correctly identified as deafness-associated genes." (PMID 36803022, 2023).
depression (2 papers, 2011 to 2023). "Mutation in RRM2B is reported to cause Autosomal-Dominant Progressive External Ophthalmoplegia with variable symptoms including depression." (PMID 37398042, 2023). "Given the typical symptoms of major depressive disorder in the present case, RRM2B should be added to the list of genes causal for PEO associated with mood disorders." (PMID 21951382, 2011). "Notably among the hub genes identified, DNMT1, RRM2B and GCA have previously been shown to be associated with suicide or depression." (PMID 37398042, 2023).
diabetes (2 papers, 2014 to 2022). "In case series of patients with mutations in RRM2B and OPA1, the prevalence of diabetes was 3.2% and 3.5%, respectively, comparable with the prevalence of diabetes in the background population." (PMID 35552684, 2022).
epilepsy (2 papers, 2015 to 2025). A brain disorder characterized by episodes of abnormally increased neuronal discharge resulting in transient episodes of sensory or motor neurological dysfunction, or psychic dysfunction. "According to the ROC curves, the expression level of key genes including CTSD, CREG1, PECAM1, ZNF101, RRM2B, MARCKSL1, and MAP2K4 demonstrated a certain accuracy in classifying epilepsy and control groups (0.7 < AUC < 0.9)." (PMID 40520613, 2025).
hearing loss (2 papers, 2015 to 2023). "Site-specific mutations in COL1A1, GJC3, RRM2B, SALL4, and SALL1 cause otosclerosis ([MIM:120150]), delayed hearing sensitivity ([MIM:611925]), sensorineural deafness ([MIM: 604712]), hearing loss ([MIM:607343]) and ear dysplasia ([MIM:602218]), among other deafness-related disorders." (PMID 36803022, 2023).
Huntington disease (2 papers, 2015 to 2025). Huntington disease (HD) is a rare neurodegenerative disorder of the central nervous system characterized by unwanted choreatic movements, behavioral and psychiatric disturbances and dementia. "When removing count-based terms, we visualized 11 signals from four Huntington’s disease modifier genes (MSH3 n = 8, LIG1 n = 1, MLH1 n = 1, RRM2B n = 1), some of which are related to neurological processes that could be relevant to Huntington’s disease." (PMID 39801710, 2025). "LIG1 and RRM2B were both associated with neurofibrillary tangles, which may provide a link to a potential role in mHTT aggregates, while MSH3 was associated with several cortical morphology-related traits relevant to Huntington’s disease." (PMID 39801710, 2025). "A total of five Huntington’s disease modifier genes (FAN1, MLH1, MSH3, PMS2 and RRM2B) had OMIM phenotype entries, mainly for cancer-related diseases for DNA-repair-related genes." (PMID 39801710, 2025).
metastatic disease (2 papers, 2013 to 2023). "IHC on PNR tumors using an antibody recognizing both Rrm2 and Rrm2B proteins showed an increase of the number of (Rrm2 + Rrm2B)+ cells in the metastatic tumors compared to the primary tumors." (PMID 36882565, 2023). "RRM2B status was significantly associated with median age at randomization (P = 0.03), bone metastases (P = 0.03), HER2 status (P = 0.01), prior chemotherapy for locally advanced or metastatic disease (P = 0.02), and PAM50 subtype (P = 0.0004)." (PMID 24215511, 2013).
small cell lung carcinoma (2 papers, 2017 to 2019). Small cell lung cancer (SCLC) is a highly aggressive malignant neoplasm, accounting for 10-15% of lung cancer cases, characterized byrapid growth, and early metastasis. "We found that the mRNA expression of RRM1, RRM2, and RRM2B genes were up-regulated in 57.9% (11 of 19), 78.9% (15 of 19), and 0% (0 of 9), respectively, of the Oncomine cancer studies covering the four subtypes of LUSC, LUAD, large cell lung carcinoma (LCLC), and small cell lung carcinoma (SCLC)." (PMID 31637211, 2019).
and neck cancer (1 paper, 2021). "Here, using data from TCGA, we found that RRM2B-amplified tumors not only exhibit increased RRM2B expression in multiple cancers (such as breast, ovarian, head, and neck cancer), but also exhibit distinct mutation signatures." (PMID 33868369, 2021).
autoimmune disease (1 paper, 2025). A disorder resulting from loss of function or tissue destruction of an organ or multiple organs, arising from humoral or cellular immune responses of the individual to their own tissue constituents. "STX8 and YES1 are implicated in T-cell activation, MAP4K5, RRM2B, FOXO1, ERBB2IP and INPPL1 can promote inflammation and KIM1, MVK and BANK1 have been associated with autoimmune diseases." (PMID 40247373, 2025).
breast tumor (1 paper, 2013). "In summary, this study revealed the occurrence of RRM1 and RRM2B aberrations in primary breast tumor specimens." (PMID 24215511, 2013). "This study demonstrated the presence of RRM1 and RRM2B copy number changes in primary breast tumor specimens." (PMID 24215511, 2013).
glomerulonephritis (1 paper, 2012). A renal disorder characterized by damage in the glomeruli. "Disturbance in renal function was present in three patients, resulting from obstructive uropathy (two patients) and glomerulonephritis (one patient), with no reports of proximal renal tubulopathy, a common finding in children with RRM2B mutations and mitochondrial DNA depletion." (PMID 23107649, 2012).
head and neck cancer (1 paper, 2021). A primary or metastatic malignant neoplasm affecting the head and neck. "Similarly, increased metastasis and poor prognosis were correlated with RRM2B overexpression in head and neck cancer, esophageal cancer and lung sarcomatoid carcinoma." (PMID 33868369, 2021).
hepatoblastoma (1 paper, 2023). Hepatoblastoma (HB) is a malignant hepatic tumor and is the most common pediatric liver cancer. "In hepatoblastoma, the RRM2 subunit of ribonucleotide reductase is associated with disease progression, but in response to chemotherapy, subunit switching favours the less active RRM2B subunit which supports hepatoblastoma cell survival and relapse." (PMID 36882565, 2023).
hepatopathy (1 paper, 2016). "Unlike subjects #3 and #11 with RRM2B mutations and typical findings of mtDNA depletion induced hepatopathy, the liver of ID#12 showed near normal mtDNA copy number and no steatosis." (PMID 27483465, 2016).
Liver disease (1 paper, 2016). "Liver disease, including ALF, has not been reported in any of the cases of recessively or dominantly inherited RRM2B-associated neuromuscular disorder." (PMID 27483465, 2016).
lung neoplasm (1 paper, 2024). A benign or malignant, primary or metastatic neoplasm involving the lungs. "Earlier studies demonstrated that broad overexpression of Rrm2 or Rrm2b induces lung neoplasms in transgenic mice." (PMID 39360631, 2024).
mesothelioma (1 paper, 2012). A usually malignant and aggressive neoplasm of the mesothelium which is often associated with exposure to asbestos. "RRM2B role in mesothelioma is unknown, but a role in pemetrexed resistance is highly plausible regarding its role upstream of TS and a central role in DNA metabolism." (PMID 22905093, 2012).
muscle disorders (1 paper, 2022). "In the development of prospective therapies for muscle disorders due to disease or aging, Rrm2b may be a potential therapeutic target for improving and/or rejuvenating muscle regenerative capacity." (PMID 35906243, 2022). "Overall, Rrm2b in the myofibers plays a critical role in modulating the MuSC fate by modifying the microenvironment, and it may lead to a possible strategy to treat muscle disorders." (PMID 35906243, 2022).
myeloma (1 paper, 2019).
non-Hodgkin lymphoma (1 paper, 2021). Distinct from Hodgkin lymphoma both morphologically and biologically, non-Hodgkin lymphoma (NHL) is characterized by the absence of Reed-Sternberg cells, can occur at any age, and usually presents as a localized or generalized lymphadenopathy associated with fever and weight loss. "Deletions of RRM2B were only observed in Non-Hodgkin’s lymphoma (∼2%)." (PMID 33868369, 2021).
oropharyngeal carcinoma (1 paper, 2019). Carcinoma, predominantly squamous cell, arising from the epithelial cells of the oropharynx. "DNA microarray analysis has shown that the gene set regulating cell-cycle progression was significantly enriched in p53R2 (the alias of RRM2B)-silenced human KB oropharyngeal carcinoma cells." (PMID 31637211, 2019).
osteosarcoma (1 paper, 2023). A usually aggressive malignant bone-forming mesenchymal neoplasm, predominantly affecting adolescents and young adults.
plasmacytic neoplasms (1 paper, 2015). "A study on a Rrm2b-knockout animal model indicated that the intactness of the RRM2B subunit is critical for maintaining chromosomal stability and that the loss of RRM2B results in plasmacytic neoplasms." (PMID 26089597, 2015).
renal failure (1 paper, 2014). "Mutations in RRM2B null mice suffer from renal failure, growth retardation, and early mortality and show decreased mtDNA content in kidney, muscle and liver." (PMID 24484525, 2014).
sarcopenia (1 paper, 2024). Progressive decline in muscle mass due to aging which results in decreased functional capacity of muscles. "RRM2B was recognized as one of the mediators participating in the effect of SGLT1 inhibition on sarcopenia." (PMID 39474649, 2024).
Stroke (1 paper, 2019). Sudden impairment of blood flow to a part of the brain due to occlusion or rupture of an artery to the brain. "However, literature retrieval results showed little evidences that other hub genes MPP4, RRM2, RRM2B, RRM1 and VCP contributed to the molecular mechanism of stroke prognosis." (PMID 31690277, 2019).
cancer (35 papers, 2008 to 2025). A tumor composed of atypical neoplastic, often pleomorphic cells that invade other tissues. "To further study associations of RRM1, RRM2, and RRM2B expression in different cancer types and TNM stages, we downloaded and analyzed the RNA-seq and clinicopathologic data of 31 types of cancer from TCGA." (PMID 31637211, 2019). "Thus, the different co-expressed gene networks are compatible with the opposite roles and different underlying mechanisms of RRM2 and RRM2B in different types of cancers, which further stressed the importance of the rationale of the use of RR inhibitors in precision cancer medicine." (PMID 31637211, 2019). "Overall, in this study we provide an in silico analysis of RRM2B alterations in cancer and their potential significance." (PMID 33868369, 2021). "Further studies in cellular models are warranted to delineate the role of RRM2B, and other 8q-chromosome genes in cancer cell maintenance, therapeutic targeting and clinical outcomes." (PMID 33868369, 2021). "We also observed that the chromosomal region 8q22.3–8q24, is amplified in multiple tumors, and includes RRM2B, MYC along with several other cancer-associated genes." (PMID 33868369, 2021). "In multiple cancers, we identified that RRM2B and/or MYC were amplified as part of an amplicon with multiple other 8q-genes (list of cancer relevant genes and gene ontology classification)." (PMID 33868369, 2021). "An analysis of genes within this 8q-amplicon showed that cancers that have both RRM2B-amplified along with MYC have a distinct pattern of amplification compared to cancers that are unaltered or those that have amplifications in RRM2B or MYC only." (PMID 33868369, 2021). "In contrast, the RRM2B gene showed a significantly lower expression in the cancer tissues in all the TNM stages." (PMID 31637211, 2019). "In contrast, RRM1, RRM2, and RRM2B were ranked in the top 10% of the down-regulated DEGs in only 8.4% (30 of 358), 4.5% (16 of 355), and 4.8% (10 of 209) of the cancer studies, respectively." (PMID 31637211, 2019). "In human cancers, the mutation rates of RRM1, RRM2, and RRM2B are all below 0.5%, based on the data from COSMIC and cBioPortal." (PMID 31637211, 2019). "We found that the mRNA expression levels of RRM1, RRM2, and RRM2B ranked in the top 10% of the up-regulated DEGs in 24.0% (86 of 358), 38.3% (136 of 355), and 10.5% (22 of 209) of the identified cancer studies, respectively." (PMID 31637211, 2019). "In contrast, the expression of RRM2B in these cancers varied, and the correlations between the expression of RRM1 and RRM2B were weak and variably dependent on cancer type." (PMID 31637211, 2019). "In accordance with these results, we observed that when FOXO3 was overexpressed, RRM2B was induced and the proliferation of cancer cells was inhibited (Figure 4biii)." (PMID 24947616, 2014). "Next, colorimetric MTS cell proliferation assays were performed to examine how RRM2B or FOXO3 expression affected the growth of cancer cells." (PMID 24947616, 2014). "In accordance with these findings, the current results indicate that FOXO3 can activate and regulate RRM2B and inhibit the growth of cancer cells." (PMID 24947616, 2014).
cancer (continued). "We obtained results indicating that patients expressing high/high FOXO3/RRM2B levels exhibited superior outcomes regarding the death rate and cancer recurrence or metastasis rate, compared with that of the patients in the low/low group." (PMID 24947616, 2014). "Moreover, cancer cells are reported to have multiple mutations in other regions of hRRM1, as well as in other RNR subunits, RRM2 and RRM2B, that possibly also can negatively impact dNTP pools." (PMID 39360631, 2024). "RRM2B has been reported to contribute to stress response and drug resistance of cancer cells." (PMID 36882565, 2023). "Here, using TCGA studies, we investigated RRM2B alterations in cancer." (PMID 33868369, 2021). "Finally, studies in cellular models are required to delineate the role of RRM2B, and other 8q-chromosome genes in cancer cell maintenance, therapeutic targeting and clinical outcomes." (PMID 33868369, 2021). "RRM2B amplification may be driven by selection of RRM2B function, or RRM2B may be amplified as a passenger, concurrent with selection for a nearby gene with a driver activity in cancer." (PMID 33868369, 2021). "Thus, to confirm increased expression, we used mRNA expression data from three TCGA studies (OV, BRCA, HNSC), and found that tumors with gains and amplifications had significantly increased RRM2B mRNA expression in all three cancer types studied." (PMID 33868369, 2021). "While MYC is the main driver for these tumors, the amplification RRM2B and the other 8q-genes may be relevant for cancer cell survival, with therapeutic implications." (PMID 33868369, 2021). "Based on these results, we hypothesize that while MYC may be the cancer driver, co-amplification of RRM2B and other 8q-genes may be relevant for cancer cell survival." (PMID 33868369, 2021). "While germline RRM2B mutations have been implicated in mitochondrial disorders, its relevance to cancer has not been established." (PMID 33868369, 2021). "Previous studies have not shown whether tumors carrying amplified RRM2B have increased RRM2B expression, which might directly impact its role in cancer." (PMID 33868369, 2021). "Notably, the expression of RRM2 and RRM2B were much weaker or even reversely correlated in some types of cancers." (PMID 31637211, 2019). "RRM2B may suppress cancer cell proliferation partially by upregulation of p21 and downregulation of cyclin D1 in addition to playing a critical role in DNA repair." (PMID 31637211, 2019). "However, if the optimal expression was used as a cutoff point, the cancer survivals predicted by RRM2B also trended differentially in the LUAD and LUSC patients, similar to the findings in the KM-plotter cohort." (PMID 31637211, 2019). "Hence, decreased RRM2B expression in PLAURsi cells can negatively regulate survival of cancer cells and provide a strong link of PLAUR to kidney damage pathways." (PMID 29254187, 2017). "Thus, RRM2B provides cancer cells with the ability to replicate DNA and therefore avoid accumulation of DNA damage in hypoxia." (PMID 29254187, 2017). "Over-expression of RRM2B in cancer cells reduced intracellular reactive oxygen species (ROS) and protected the mitochondrial membrane potential against hydrogen peroxide, demonstrating RRM2B’s involvement in anti-oxidation." (PMID 26733354, 2016). "Hence, PYCR1 is a potential target for novel chemotherapeutic agent development, not only as a means to inhibit tumor cell growth, but also to sensitize existing cancer cells that express RRM2B to ionizing radiation and other modalities." (PMID 26733354, 2016). "RRM2B can suppress the metastasis and proliferation of different cancer cells." (PMID 26089597, 2015). "Furthermore, RRM2B expression is correlated with improved survival in some cancers, whereas a more progressive phenotype of certain other cancers complicates the RRM2B regulatory pathway." (PMID 26089597, 2015).